MIR3680-1 (microRNA 3680-1)
Synonyms: hsa-mir-3680; MIR3680; hsa-mir-3680-1
Gene: MicroRNA gene on chromosome 16 (21,506,049 to 21,506,135, reverse strand). Ensembl gene ENSG00000265462.
Homologues: Paralogues in human: MIR3680-2 (100% identical).